PRKCA (protein kinase C alpha)
Description:
Calcium-activated, phospholipid- and diacylglycerol (DAG)- dependent serine/threonine-protein kinase that is involved in positive and negative regulation of cell proliferation, apoptosis, differentiation, migration and adhesion, tumorigenesis, cardiac hypertrophy, angiogenesis, platelet function and inflammation, by directly phosphorylating targets such as RAF1, BCL2, CSPG4, TNNT2/CTNT, or activating signaling cascade involving MAPK1/3 (ERK1/2) and RAP1GAP. Involved in cell proliferation and cell growth arrest by positive and negative regulation of the cell cycle. Can promote cell growth by phosphorylating and activating RAF1, which mediates the activation of the MAPK/ERK signaling cascade, and/or by up-regulating CDKN1A, which facilitates active cyclin-dependent kinase (CDK) complex formation in glioma cells. In intestinal cells stimulated by the phorbol ester PMA, can trigger a cell cycle arrest program which is associated with the accumulation of the hyper-phosphorylated growth-suppressive form of RB1 and induction of the CDK inhibitors CDKN1A and CDKN1B. During macrophage differentiation induced by macrophage colony-stimulating factor (CSF1), is translocated to the nucleus and is associated with macrophage development. After wounding, translocates from focal contacts to lamellipodia and participates in the modulation of desmosomal adhesion. Plays a role in cell motility by phosphorylating CSPG4, which induces association of CSPG4 with extensive lamellipodia at the cell periphery and polarization of the cell accompanied by increases in cell motility. During chemokine-induced CD4(+) T cell migration, phosphorylates CDC42-guanine exchange factor DOCK8 resulting in its dissociation from LRCH1 and the activation of GTPase CDC42. Is highly expressed in a number of cancer cells where it can act as a tumor promoter and is implicated in malignant phenotypes of several tumors such as gliomas and breast cancers. Negatively regulates myocardial contractility and positively regulates angiogenesis, platelet aggregation and thrombus formation in arteries. Mediates hypertrophic growth of neonatal cardiomyocytes, in part through a MAPK1/3 (ERK1/2)-dependent signaling pathway, and upon PMA treatment, is required to induce cardiomyocyte hypertrophy up to heart failure and death, by increasing protein synthesis, protein-DNA ratio and cell surface area. Regulates cardiomyocyte function by phosphorylating cardiac troponin T (TNNT2/CTNT), which induces significant reduction in actomyosin ATPase activity, myofilament calcium sensitivity and myocardial contractility. In angiogenesis, is required for full endothelial cell migration, adhesion to vitronectin (VTN), and vascular endothelial growth factor A (VEGFA)-dependent regulation of kinase activation and vascular tube formation. Involved in the stabilization of VEGFA mRNA at post-transcriptional level and mediates VEGFA-induced cell proliferation. In the regulation of calcium-induced platelet aggregation, mediates signals from the CD36/GP4 receptor for granule release, and activates the integrin heterodimer ITGA2B-ITGB3 through the RAP1GAP pathway for adhesion. During response to lipopolysaccharides (LPS), may regulate selective LPS-induced macrophage functions involved in host defense and inflammation. But in some inflammatory responses, may negatively regulate NF-kappa-B-induced genes, through IL1A-dependent induction of NF-kappa-B inhibitor alpha (NFKBIA/IKBA). Upon stimulation with 12-O-tetradecanoylphorbol-13-acetate (TPA), phosphorylates EIF4G1, which modulates EIF4G1 binding to MKNK1 and may be involved in the regulation of EIF4E phosphorylation. Phosphorylates KIT, leading to inhibition of KIT activity. Phosphorylates ATF2 which promotes cooperation between ATF2 and JUN, activating transcription. Phosphorylates SOCS2 at 'Ser-52' facilitating its ubiquitination and proteasomal degradation (By similarity). Phosphorylates KLHL3 in response to angiotensin II signaling, decreasing the interaction between KLHL3 and WNK4. Phosphorylates and activates LRRK1, which phosphorylates RAB proteins involved in intracellular trafficking.
Synonyms: PKC-alpha; PKCA; PKCα; AAG6; PKCI+/-; PKCalpha
Tractability: Small molecule: an approved drug acts on it; a structure with a bound ligand is known; a high-quality ligand is known; it has a high-quality binding pocket; it belongs to a druggable protein family. Antibody: UniProt places it where antibodies can reach, with high confidence; its Gene Ontology location is reachable by antibodies, with high confidence; the Human Protein Atlas places it where antibodies can reach. PROTAC: ubiquitination databases record sites on it; its protein half-life has been measured; a small molecule that binds it is known.
Target class: AGC protein kinase PKC family; AGC protein kinase PKC alpha subfamily; Enzyme; Kinase; AGC protein kinase group; Protein Kinase
Safety:
Unwanted effects reported when the protein is acted on. In parentheses: how it was acted on, where the effect was seen, and who reports it.
heart disease (cardiovascular system; source: Force et al. (2011))
Gene: Protein-coding gene on chromosome 17 (66,302,613 to 66,810,743, forward strand). Ensembl gene ENSG00000154229.
Subcellular location: Cytoplasm; Cell membrane; Mitochondrion membrane; Nucleus
Subcellular location (Human Protein Atlas): Cytosol; Plasma membrane; Vesicles
Pathways (Reactome):
Signal Transduction: Ca2+ pathway; Calmodulin induced events; EGFR Transactivation by Gastrin; G alpha (z) signalling events; RHO GTPases Activate NADPH Oxidases; Regulation of KIT signaling; SHC1 events in ERBB2 signaling; Signaling by SCF-KIT; VEGFR2 mediated cell proliferation; WNT5A-dependent internalization of FZD4
Developmental Biology: RET signaling; ROBO receptors bind AKAP5
Hemostasis: Disinhibition of SNARE formation; Response to elevated platelet cytosolic Ca2+
Cell Cycle: Depolymerization of the Nuclear Lamina
Extracellular matrix organization: Syndecan interactions
Metabolism: Acetylcholine regulates insulin secretion
Metabolism of RNA: HuR (ELAVL1) binds and stabilizes mRNA
Neuronal System: Trafficking of GluR2-containing AMPA receptors
Sensory Perception: Inactivation, recovery and regulation of the phototransduction cascade
Gene Ontology:
Molecular function: calcium,diacylglycerol-dependent serine/threonine kinase activity; enzyme binding; histone H3T6 kinase activity; protein binding; protein kinase activity; protein serine/threonine kinase activity; diacylglycerol binding; diacylglycerol-dependent serine/threonine kinase activity; integrin binding; ATP binding; protein serine kinase activity; signaling receptor binding; zinc ion binding
Biological process: desmosome assembly; negative regulation of dopamine receptor signaling pathway; negative regulation of glial cell apoptotic process; positive regulation of angiogenesis; positive regulation of angiotensin-activated signaling pathway; positive regulation of blood vessel endothelial cell migration; positive regulation of cell adhesion; positive regulation of cell migration; positive regulation of endothelial cell migration; positive regulation of endothelial cell proliferation; positive regulation of lipopolysaccharide-mediated signaling pathway; positive regulation of mitotic cell cycle; protein kinase C signaling; protein phosphorylation; regulation of focal adhesion assembly; regulation of platelet aggregation; response to interleukin-1; apoptotic signaling pathway; intracellular signal transduction; mitotic nuclear membrane disassembly; negative regulation of cytokine production involved in inflammatory response; positive regulation of adenylate cyclase-activating G protein-coupled receptor signaling pathway; positive regulation of bone resorption; positive regulation of cardiac muscle hypertrophy; positive regulation of dense core granule biogenesis; and 22 more
Cellular component: ciliary basal body; cytoplasm; cytosol; endoplasmic reticulum; extracellular exosome; mitochondrial membrane; mitochondrion; plasma membrane; alphav-beta3 integrin-PKCalpha complex; nucleoplasm; nucleus; perinuclear region of cytoplasm; protein-containing complex
Genetic constraint (gnomAD): Loss-of-function variants: 23 observed, 82.09 expected, observed/expected ratio (o/e) 0.28, 90% interval 0.2 to 0.4. The upper end of that interval is the gene's LOEUF score, 0.4, which puts it in group 1 of 6, group 1 being the genes least tolerant of losing a copy. Missense variants: 501 observed, 867.28 expected, observed/expected ratio (o/e) 0.58, 90% interval 0.54 to 0.62. Synonymous variants: 326 observed, 318.74 expected, observed/expected ratio (o/e) 1.02, 90% interval 0.93 to 1.12.
Homologues: Orthologues: chimpanzee PRKCA (99% identical), macaque PRKCA (99% identical), mouse Prkca (99% identical), rat Prkca (99% identical), dog PRKCA (99% identical), pig PRKCA (99% identical), rabbit PRKCA (91% identical), guinea pig PRKCA (86% identical), zebrafish prkcaa (84% identical), zebrafish prkcab (78% identical), Caenorhabditis elegans pkc-2 (69% identical), Drosophila melanogaster Pkc53E (67% identical), and 5 more. Paralogues in human: PRKCB (80% identical), PRKCG (72% identical), PRKCE (37% identical), PRKCH (35% identical), PKN2 (34% identical), PKN1 (33% identical), PRKCI (32% identical), PRKCZ (32% identical), PKN3 (31% identical).
Diseases named in the same sentence as PRKCA in open-access papers:
PRKCA is named in the same sentence as 305 diseases in open-access papers, as found by Europe PMC text mining. Sharing a sentence is not in itself a finding about the gene and the disease. The quoted sentences say what the papers report.
breast carcinoma (110 papers, 2000 to 2025). "The protein kinase C alpha (PKCα) is implicated in cancer progression and associated with a poor prognosis in breast cancer patients." (PMID 31731625, 2019). "Protein kinase C alpha (PKCα) is a serine-threonine protein kinase implicated in cancer metastasis and associated with poor prognosis in breast cancer patients." (PMID 29216867, 2017). "PRKCA overexpression is strongly associated with a more invasive and metastatic phenotype in breast cancer." (PMID 23497265, 2013). "PRKCA is a serine/threonine-protein kinase that is highly expressed in a number of cancer cells where it can act as a tumor promoter and is implicated in malignant phenotypes of several tumors such as gliomas and breast cancers." (PMID 27993151, 2016). "PRKCA serves as a pivotal signaling hub and a potential therapeutic target in breast cancer stem cells, which exhibit comparable cell surface marker profiles to those observed in TNB." (PMID 38418940, 2024). "The interaction mediates ER Ca2+ leakage and increases in cytosolic Ca2+, thereby activating protein kinase C alpha and enhancing breast cancer cell migration." (PMID 38971758, 2024). "Network pharmacology analysis revealed classical protein kinase C α-type (PRKCA) to be involved in majority of pathways identified in breast cancer." (PMID 38081857, 2023). "Protein kinase C alpha (PRKCA) is associated with metastasis and poor outcome in breast cancer and lung cancer patients." (PMID 35158795, 2022). "MCF-7 breast cancer cells transfected with protein kinase C-alpha (PKC-α) showed a higher proliferative rate, anchorage-independent growth, and increased tumorigenicity in vivo." (PMID 36476410, 2022). "Ten genes, including CCNB1, CDH1, KDR, RAB25, PRKCA, etc., found which can maintain the high accordance of mRNA–protein for both breast cancer patients and cell lines in basal-like subtypes for the first time." (PMID 36360219, 2022). "The collective evidence suggests that PRKCA is an important candidate for breast carcinoma stem cell management." (PMID 35589867, 2022). "PRKCA is upregulated in several human cancer types including breast cancer, nonsmall‐cell lung cancer, and hematological malignancies." (PMID 35128835, 2022). "The greatest number of fusions was detected for PRKCA with 43 fusions identified, and the majority of these (19 fusions) were found in breast cancer samples." (PMID 33617877, 2021). "For example, miR-216a overexpression can promote breast cancer cell apoptosis by targeting protein kinase C alpha (PKCα) and increase cell apoptosis in response to gemcitabine in the pancreatic cancer cells." (PMID 35046806, 2021). "A previous report indicated that miR-216a induced the apoptosis of breast cancer cells by downregulating PRKCA." (PMID 32681720, 2020). "We previously reported that stable transfection of protein kinase C alpha (PKCα) into T47D human breast cancer cells results in tamoxifen (TAM)-resistant tumour growth." (PMID 12778068, 2003). "PRKCA mediates the expression of CATB in a human breast cancer cell line." (PMID 38542221, 2024). "However, there is still scope to understand the role of PRKCA in breast cancer as much is still to be uncovered." (PMID 38081857, 2023). "Low PRKCA mRNA expression was statistically associated with a best RFS of breast cancer patients with negative estrogen receptor tumors (HR = 1.36, p = 0.027), while RARA mRNA expression did not affect RFS probability." (PMID 33723318, 2021). "This may additionally lead to enhanced activation of other MZF1 target genes that are important for amplification of breast cancer signaling networks and promoting breast cancer cell migration and invasion, such as PRKCA." (PMID 31963147, 2020). "So we first checked the expression levels of PRKCA in breast cancer cell lines." (PMID 28515445, 2017).
breast carcinoma (continued). "Furthermore, it has been shown that PRKCA expression is increased in the invasive breast cancer cell lines MDA-MB-231 and HS578T, and overexpression can lead to a significant increase in both the migration and invasion ability of the cell lines." (PMID 23497265, 2013). "The predictions revealed that the mechanism of sinapic acid in breast cancer may be due to multiple pathways and proteins like β-catenin, PRKCA, CASP8, and cytochrome enzymes (CYP1A1 and CYP3A4); the majorly regulated pathway was predicted to be “Pathways in cancer”." (PMID 38081857, 2023). "Hence, PRKCA could be a potent target to be suppressed for a better treatment strategy to control breast cancer." (PMID 38081857, 2023). "Most of these genes were associated with cancers of metabolic systems (DUSP6, SGK1, BMP4, RASGRF1, GDF15) followed by breast cancer (CACNA2D3, ITGB7), cancers of the central nervous system (PRKCA), or leukemia (MECOM, JAK3)." (PMID 36624125, 2023). "Clinically, PRKCA is a target for types of cancer including acute myeloid leukemia (AML), breast cancer, and ovarian cancer." (PMID 36531045, 2022). "In this line, it has been established that in breast cancer, resistin induced the phosphorylation of proto-oncogene tyrosine-protein kinase Src (c-Src), protein phosphatase 2A (PP2A), and protein kinase C alpha (PKCα), among others, promoting cancer progression." (PMID 37238961, 2023). "Interestingly, a complex formation between Elk-1 and MZF1 has been shown to enhance PRKCA expression in a synergistic manner and its expression correlates positively with the expression of Elk1 and MZF1 in various breast cancer cell lines." (PMID 31963147, 2020). "The predictions revealed that the mechanism of sinapic acid in breast cancer may be due to regulation of multiple proteins like CTNNB1, PRKCA, CASP8, SIRT1, and cytochrome enzymes (CYP1A1 & CYP3A4); the majorly regulated pathway was predicted to be ‘Pathways in cancer’." (PMID 38081857, 2023). "However, protein levels of PRKCA, a predicted miR-34c target and a known regulator of breast cancer cell proliferation were not influenced by miR-34c." (PMID 25064703, 2014).
glioma (37 papers, 1999 to 2025). A benign or malignant brain and spinal cord tumor that arises from glial cells (astrocytes, oligodendrocytes, ependymal cells). "Specifically, PRKCA overexpression is associated with increased proliferation and decreased apoptosis in gliomas, bladder cancer and prostate carcinomas." (PMID 27144431, 2016). "Although no previous studies have suggested direct associations between genes, including AR and PRKCA or pathways in cancer, gliomas, ErbB signaling pathway, and CTEPH, they led to our hypothesis that AR, PRKCA, and pathways in cancer, gliomas, and ErbB signaling pathway are associated with CTEPH." (PMID 28904974, 2017). "The investigated ddPCR-based assays enable the detection of diagnostically relevant glioma-associated mutations in the IDH1, IDH2, H3-3A, BRAF, and PRKCA genes, as well as in the TERT promoter." (PMID 35361262, 2022). "PRKCA, also a target gene of hsa-miR-3148, was enriched in pathways in cancer, glioma, and ErbB signaling pathway." (PMID 28904974, 2017). "PRKCA is also overexpressed in glioma and small-cell lung cancer and involved in several pathways of signal transduction, cellular communication and immune system, among them the VEGF and the ErbB signalling pathway." (PMID 19662092, 2009). "The other six investigated glioma samples showed the PRKCA D463-wildtype sequence." (PMID 35361262, 2022). "Protein kinase C Alpha (PRKCA), also a target gene of hsa-let-7i-5p and has-miR-320a, was enriched in 14 of 18 KEGG pathways, such as pathways in cancer, glioma, and PI3K-Akt signaling pathway." (PMID 34122072, 2021). "Protein kinase C Alpha (PRKCA), also a target gene of hsa-let-7i-5p and has-miR-320a, was enriched in 14 of 18 KEGG pathways, such as in cancer, glioma, and PI3K-Akt signaling pathway." (PMID 34122072, 2021). "PRKCA (Protein Kinase C Alpha), also a target gene of hsa-miR-3148, was enriched in 15 of 16 KEGG pathways, such as pathways in cancer, glioma, and ErbB signaling pathway." (PMID 28904974, 2017). "We found two new occurrences of PRKCA (protein kinase C, alpha) fusions in lung squamous cell carcinoma and three PRKCB (protein kinase C, beta) fusions in lung squamous cell carcinoma, lung adenocarcinoma and low-grade glioma." (PMID 25204415, 2014). "This supports the concept that PKCα-D463H may regulate transcription through targetable epigenetic mechanisms, providing a potential clinical strategy for PRKCA mutant choroid glioma, particularly as BET domain inhibitors have been proposed for use in other glioma settings." (PMID 41187221, 2025).